LGR4 (leucine rich repeat containing G protein-coupled receptor 4)
Diseases named in the same sentence as LGR4 in open-access papers (continued):
Sharing a sentence is not in itself a finding about the gene and the disease.
tumor (36 papers, 2011 to 2026). "Activation of the RSPOs/LGR4/ERK/STAT3 pathway by LGR4 drives the M2 polarization of Tumor-Associated Macrophages (TAMs)." (PMID 41357583, 2025). "For example, LGR4 (encoded by LGR4) and its ligands R-spo1-4 are not only a vital axis for tumor growth and metastasis but also promotes macrophage M2 polarization and tumor-associated macrophage (TAM) formation." (PMID 33386920, 2021). "LGR4 can promote tumor-associated macrophages (TAMs) M2 polarization due to the activity of RSPOs/LGR4/ERK/STAT3 signaling." (PMID 33946652, 2021). "LGR4-deficient mice show retarded skin tumors and smaller tumor structures compared to wild-type mice." (PMID 33946652, 2021). "In univariate analysis, high expression of GPR48/LGR4 was significantly associated with several clinicopathologic parameters including tumor size (P=0.050), LN metastasis (P=0.004), locoregional recurrence (P=0.037), and presence of BRAFV600E (P=0.003)." (PMID 29383135, 2017). "Knockdown of GPR48/LGR4 in tumor cells was significantly associated with reduced phosphorylation of Ser9 of GSK3β and ERK1/2, resulting in downregulation of β-catenin signaling." (PMID 29383135, 2017). "LGR4 has been implicated in many physiological processes including embryonic development, cell motility, and tumor metastasis." (PMID 25811370, 2015). "Dysregulatin on RSPO3 (a R‐spondins ligand of LGR4)‐LGR4 signaling in LUAD with Keap1 deficiency could facilitate tumor aggressiveness." (PMID 40364562, 2025). "Thus, GPR48/LGR4 positivity was highly associated with markers of tumor aggressiveness." (PMID 29383135, 2017). "In this study, we found that RSPO4 suppressed EMT and tumor cell stemness through Wnt/β-catenin signaling in an LGR4/5 dependent manner." (PMID 41522353, 2026). "More importantly, the author and other researchers found that LGR4 plays an important role in the pathophysiology of bone metabolic disease and tumor bone metastasis." (PMID 40469438, 2025). "Tumor stage and the ADGRD1, ADGRE3, and LGR4 genes were identified to be independently associated with the prognosis of patients with LUAD." (PMID 40364562, 2025). "One approach involves the inhibition of the R-spondin-Leucine-rich repeat containing G-protein coupled receptor 4 (R-spondin/LGR4) signaling, which is crucial for pro-tumor M2 macrophage polarization." (PMID 40872475, 2025). "In conclusion, LGR4 plays an important role in tumor bone metastasis and is a potential target worthy of further in-depth study." (PMID 40469438, 2025). "This soluble LGR4-ECD for clinical treatment of tumor bone metastases is very promising for application." (PMID 40469438, 2025). "LGR4 plays a dual role in bone metabolism and tumor bone metastasis, both in maintaining bone metabolic homeostasis and promoting tumor cell metastasis to bone tissue." (PMID 40469438, 2025). "In both TCGA‐LUAD, in the GSE30219 and GSE18842 cohorts, the expression of ADRB1, ADGRD1, and ADGRE3 were reduced, whereas the expression of OR51E1 and LGR4 were elevated in tumor samples." (PMID 40364562, 2025). "The Leucine-rich repeat-containing G protein-coupled receptor 4 (LGR4) is a member of the G protein-coupled receptor family and plays an important role in bone metabolism and tumor bone metastasis." (PMID 40469438, 2025). "In vitro experiments showed that compared with 2D GC cell culture, the expression of ONECUT2 protein and stemness-related markers CD44, SOX9, SOX2, and LGR4 simultaneously increased in 3D tumor stem cell spheroid culture." (PMID 38997271, 2024). "First, the expression of LGR4 in HCC tumor tissues and cell lines was detected by western blotting and immunofluorescence." (PMID 36385965, 2022). "Taken together, our data comprehensively confirm that Circ_0003945/miR‐34c‐5p/LGR4/β‐catenin pathway exerts its tumour‐promoting role in HCC progression." (PMID 35170199, 2022).
tumor (continued). "Collectively, these findings indicate LGR4/5/6 upregulation increases Wnt signaling to facilitate tumor growth and therapeutic resistance in human cancers." (PMID 35204808, 2022). "Upregulated LGR4 protein expression was also confirmed in xenograft tumor samples with high RSPO2 expression." (PMID 36217544, 2022). "Compared to normal colorectal tissues, expression levels of LGR4 are significantly lower in tumor tissues." (PMID 36008975, 2022). "MiR-449b as a tumor suppressor prevented the proliferation of NSCLC by downregulating LGR4 and LGR4 was perceived as a high-risk immune gene in NSCLC." (PMID 35140734, 2021). "Together these data pointed towards a key role for LGR4 in immune-related diseases, though further studies were needed to better establish this, especially in the field of tumor immunotherapy." (PMID 35140734, 2021). "Remarkably, LGR4 levels correlate with tumor stage and lymph node status, and high expression levels of this molecule are a poor prognosis factor for 5-year overall survival." (PMID 33946652, 2021). "At the same time, higher LGR4 positivity was observed in the normal mucosa than in the tumour tissue, with a highly significant difference (93% and 36%, P<0.0001)." (PMID 30803215, 2019). "These relationships between LGR and β-catenin proteins during carcinogenesis and possibly during tumour progression prompted us to study this protein and LGR4 in the same samples of normal and tumour gastric mucosa." (PMID 30803215, 2019). "LGR4 immunoexpression is more frequent and found in a larger number of cells in normal tissues than in tumour samples." (PMID 30803215, 2019). "The findings from this study suggest a controversial role for LGR4, related to proliferative status and inversely related to tumour progression, in contrast to most previous reports." (PMID 30803215, 2019). "The immunoexpression for LGR4 in the primary tumour in relation to the number of positive cells was significantly higher in the intestinal type (7321/21001=35%) than in the diffuse type (990/3969=25%; P<0.001)." (PMID 30803215, 2019). "More importantly, the clinical observations revealed that patients with higher expression of GPR48/LGR4 tended to experience more rapid regional tumor progression, including metastasis." (PMID 29383135, 2017). "Collectively, our results indicate that upregulation of the RSPO2–GPR48/LGR4 signaling axis promotes tumor aggressiveness in PTCs." (PMID 29383135, 2017). "We observed that RSPO2 and its receptor, GPR48/LGR4, were expressed in normal thyroid gland and at higher levels in in PTCs, particularly in patients with regional tumor progression, including lymph node (LN) metastasis." (PMID 29383135, 2017). "Most tumor cells in PTCs were GPR48/LGR4-positive, and the staining was more intense than in normal follicular cells positive for this marker." (PMID 29383135, 2017). "We evaluated protein expression in lysates from normal and PTC tissue specimens to confirm the differential expression of GPR48/LGR4 between tumor and normal tissues." (PMID 29383135, 2017). "This idea is further supported by the elevated viability and migration of tumor cells expressing higher levels of GPR48/LGR4." (PMID 29383135, 2017). "Here, we report the characterization of a panel of monoclonal LGR4 antibodies and the results of IHC analysis in selected normal and tumor tissues using LGR4-specific antibodies." (PMID 24205130, 2013). "Cluster I consisted of genes upregulated in CC cells, which included tumor-related genes such as LGR4, AGR2, PCAF, TMEM97, FRAT2, EFNB2 and ZIC2." (PMID 21333016, 2011). "By developing monoclonal antibodies and small molecule inhibitors against LGR4, we can inhibit the growth and metastasis of tumor cells in bone tissues, alleviate patients’ pain and skeletal complications, and improve patients’ survival rate and quality of life." (PMID 40469438, 2025). "LGR4, a receptor for Norrin, is involved in immune modulation within the tumor microenvironment." (PMID 41357583, 2025).
tumor (continued). "Norrin is essential for cancer cell invasion and serves as an LGR4 agonist in malignant cells, stimulating Wnt/β-catenin signaling to drive metastatic behavior through enhanced motility and tissue infiltration, thereby facilitating tumor advancement." (PMID 41357583, 2025). "In the treatment of tumor bone metastasis, LGR4 also has important application value." (PMID 40469438, 2025). "LGR4 expression is upregulated in cancers, including breast, prostate, MM, colon, lung adenocarcinomas and high-grade plasmacytoid ovarian cancer, and plays a role in tumor progression, invasion, and metastasis." (PMID 40469438, 2025). "The regulation of LGR4 may become a new strategy for the prevention and treatment of tumor bone metastasis." (PMID 40469438, 2025). "However, the regulatory mechanism of LGR4 in tumor bone metastasis is still incomplete, and further in-depth studies on the signaling pathways and regulatory networks downstream of LGR4 are needed." (PMID 40469438, 2025). "LGR4 plays a key role in promoting the metastasis of tumor cells to bone tissues, and the blockage of its signaling pathway may become an effective means for the treatment of tumor bone metastasis." (PMID 40469438, 2025). "Finally, in a cisplatin-resistant subcutaneous tumor mouse model, ALYREF knockdown significantly reduced cisplatin resistance and led to downregulation of ALYREF, LGR4, and β-Catenin protein levels in tumor tissues." (PMID 41345330, 2025). "Knockout of LGR4 significantly inhibits the tumor growth and prolongs the survival time, and increased numbers of M1 macrophages and activated CD8 + T cell infiltration are also observed, suggesting that LGR4 promotes antitumor effects by changing macrophage polarization." (PMID 35493517, 2022). "It showed that LGR4 expression was increased in the tumor tissues." (PMID 36385965, 2022). "In conclusion, Circ_0003945 exerts a tumour‐promoting role in HCC cells by regulating the miR‐34c‐5p/LGR4/β‐catenin axis, which may be a potential target for HCC therapy." (PMID 35170199, 2022). "Several studies support the idea that inhibitors of the RSPOs/LGR4/Wnt/β-catenin axis could reduce tumor progression, metastasis, and recurrence." (PMID 33946652, 2021). "The gene of LGR4 emerged as a critical player in regulation of tumor growth and progression." (PMID 35140734, 2021). "Recent evidence suggests that the LGR4/RANKL signaling activates independent pathways that could impact tumor development and stem cell behavior." (PMID 33946652, 2021). "Both Lgr5 and Lgr6, together with the other member of the same receptor family, namely Lgr4, are recognized mediators of the Wnt signalling pathway, that is activated in human HF tumours, especially TB, and probably in canine TB as well, as indicated by the presence of numerous positive nuclei." (PMID 32397255, 2020). "All these reports point to a role of the pro-carcinogenic LGR4 in promoting tumour progression." (PMID 30803215, 2019). "The cell count in the positive cases of LGR4 strengthens the information stated previously regarding the comparison between the number of normal and tumour positive cases: a much higher percentage of stained cells in the normal mucosa compared to the percentage of positive tumour cells." (PMID 30803215, 2019). "A few reports have compared the presence of LGR4 in normal and tumour mucosa." (PMID 30803215, 2019). "Although in this study LGR4 was present in tumour samples, its expression was more common in those cases without lymph node metastases, with less local invasion and in the absence of perineural invasion, i.e., associated with clinical variables of better prognosis." (PMID 30803215, 2019). "Therefore, LGR4 may be a potential target for the treatment of bone metabolic diseases and tumor bone metastasis." (PMID 40469438, 2025).
tumor (continued). "The Hippo signaling pathway, which is a critical pathway for the modulation of organ size, can be substantially considered as up-regulation, demonstrating that LGR4 may activate this pathway to modulate the proliferation of tumor size by Hippo signaling pathway." (PMID 36008975, 2022). "We found that RSPO4 FUm1/2 mutant lost its inhibitory effect on migration and invasion of both LGR4+/LGR5- and LGR4-/LGR5+ tumor cells." (PMID 41522353, 2026). "Consistently, luciferase reporter assay showed that RSPO4 FUm1/2 mutant lost the inhibitory effect on Wnt/β-catenin signaling and target genes in both LGR4+/LGR5- and LGR4-/LGR5+ tumor cell lines." (PMID 41522353, 2026). "Intriguingly, we found that RSPO4 suppressed Wnt/β-catenin signaling in both LGR4 and LGR5 expressing tumor cells." (PMID 41522353, 2026). "The key role of LGR4, a member of the GPCR family, has been demonstrated in tumor immunoregulation, and tumor immunotherapy strategies targeting LGR4 have been proposed and validated." (PMID 38217549, 2024). "(M) Representative in situ hybridization (ISH) staining of tumor sections from ApcMin/+, BC, and FBC mice using Lgr4 and Lgr5 probes." (PMID 38921956, 2024). "Researchers showed that RSPOs/LGR4-inhibition with a soluble LGR4 extracellular domain (LGR4-ECD) or an RSPOs neutralizing antibody attenuates M2-TAMs polarization and it enhances the anti-tumor activity of CD8+ T-cells." (PMID 33946652, 2021). "RSPO4 functions as a tumor suppressor by antagonizing canonical and non-canonical Wnt signaling in an LGR4/5- and ZNRF3- dependent manner." (PMID 41522353, 2026). "Therefore, LGR4/5 and ZNRF3 are required for the suppressive effect of RSPO4 expression on tumor cell migration, invasion and stemness, and RSPO4 exerts these effects through suppressing Wnt signaling." (PMID 41522353, 2026). "The level of LGR4 expression was higher in HCC cell lines and tumor tissues." (PMID 36385965, 2022). "Moreover, LGR4 knockdown in DU-145 mCRPC cells reduces the transcription of EMT and Wnt target genes, and decreases tumor burden in xenografts, suggesting LGR4 plays an oncogenic role in the prostate by potentiating Wnt signaling and EMT." (PMID 35204808, 2022). "In addition, LGR4, a member of the G-protein coupled receptor (GPCR) family, plays a key role in the regulation of tumor immunity." (PMID 35493517, 2022). "LGR4 ablation inhibited AR/CREB1 expression, promoted γH2A.X staining and reduced tumor growth." (PMID 35140734, 2021). "Interestingly, LGR4 was revealed as a third receptor for RANKL and involvement of the RANKL-LGR4 axis cannot be excluded from tumor growth." (PMID 30355966, 2018). "Nevertheless, it should be noted that RSPO2 and LGR4 are not globally expressed in all tumor cells in the Wnthigh GBM xenografts, suggesting heterogeneous property of GBM cells and their distinctive of β-catenin activity." (PMID 30337838, 2018). "Additionally, we compared the intensity and distribution of GPR48/LGR4 staining in normal thyroid and tumor tissues of patients with PTC." (PMID 29383135, 2017). "Interestingly, invasive fronts of tumor tissues exhibited high levels of GRP48/LGR4 staining, and GPR48/LGR4 was more intensely and extensively expressed in tumor lesions than in normal tissue." (PMID 29383135, 2017). "Another validated focal CNA detected in one tumor (WT201) was the 825 kb homozygous deletion at 11p14.1p14.2 (#chr11:26,688,179-27,513,817; GRCh37), harbouring BBOX, among others genes (SLC5A12, FIBIN, CCDC34, LGR4)." (PMID 26913079, 2016). "The intensity of LGR4-IR was largely uniform across different regions of each tumor, implying a lack of intratumoral heterogeneity in LGR4 expression." (PMID 24205130, 2013). "Increased staining in tumor vs normal crypts was clearly visible in Sample A. Furthermore, the staining was completely competed off in the presence of excess amounts of LGR4-ECD, providing additional evidence that the antibody is specific to LGR4." (PMID 24205130, 2013).
tumor (continued). "A positive correlation to LH was found for LGR4 that regulates expression of estrogen receptor and MR1 that mediates tumor immune escape, whereas there was a negative correlation between LH and GIT2, implicated in aging and cellular senescence." (PMID 34758873, 2021). "To investigate the expression of GPR48/LGR4 mRNA in human PTC, we analyzed paired clinical specimens of tumor and non-tumor tissues from six patients with PTC by RT-PCR." (PMID 29383135, 2017). "To quantify immunoreactivity of GPR48/LGR4 and BRAFV600E in PTC, we adopted a scoring system that combined the intensity and the distribution of positive staining: 0, no staining; +1, weak staining in focal tumor areas; +2, moderate staining in most tumors; and +3, strong staining in most tumors." (PMID 29383135, 2017).
metabolic disorders (5 papers, 2021 to 2025). "In human beings, at least 13 mutations in the LGR4 gene locus are correlated with metabolic disorders, indicating a close relation between LGR4 and metabolism." (PMID 40810739, 2025). "Although substantial genetic evidence links LGR4 variants to metabolic disorders in humans and mice, the precise mechanisms by which LGR4 influences metabolism are unclear." (PMID 39033139, 2024). "Hence, the function of LGR4 in energy metabolism was being broadly studied, a better understanding of the molecular mechanism underlying various metabolic pathways involved by LGR4 will help in future development of new treatments for metabolic diseases." (PMID 35140734, 2021). "This concept is supported by the following observations: 1) Analysis of data from publicly available databases and literature revealed that islet Lgr4 mRNA is related to metabolic disorders both in mice and human beings." (PMID 40810739, 2025). "Establishing the significance of LGR4 in these processes could potentially impact the development of therapeutic strategies for metabolic disorders." (PMID 39033139, 2024).
infection (3 papers, 2017 to 2024). The state of being infected such as from the introduction of a foreign agent such as serum, vaccine, antigenic substance or organism. "Next, we silenced Lgr4 in BMSCs using lentivirus-mediated shRNA infection (sh-Lgr4 group), and the blank lentiviral vector carrying GFP-infected cells were set as the negative control (NC group)." (PMID 28272338, 2017).
colon (1 paper, 2017). "Overexpression of GPR48/LGR4 increases phosphorylation levels of AKT and ERK1/2, and GPR48/LGR4 activates Wnt/β-catenin signaling via a PI3K- and ERK1/2-dependent mechanism in colon carcinogenesis." (PMID 29383135, 2017).
neurological disease (1 paper, 2023). "The SNP on CFA21 is located within ANO3, which has primarily been associated with neurological disease, but is also positioned in the proximity of LGR4, which is associated with cataract development in mice." (PMID 37118843, 2023).
LGR4 also shares sentences with these, for which no sentence is quoted: electrolyte imbalance (2 papers); renal fibrosis (2); thyroid tumor (2); venous ulcers (2); adenocarcinoma (1); adenoma (1); age (1); Alzheimer disease (1); anemia (1); aniridia (1); Anorexia (1); autoimmune hepatitis (1); biliary tract cancer (1); bone metastasis (1); chronic fatigue syndrome (1); chronic kidney disease (1); depression (1); ectodermal dysplasia (1); Epileptic encephalopathy (1); esophageal squamous cell carcinoma (1); Hyperglycemia (1); Hypertension (1); infectious colitis (1); inflammation (1); Insulin resistance (1); Intellectual disability (1); meningioma (1); multiple cysts of the kidneys (1); prostate intraepithelial neoplasia (1); psychiatric disorder (1).
A further 7 diseases each share a sentence with LGR4 in 1 paper.